BCL2 (BCL2 apoptosis regulator)
Diseases named in the same sentence as BCL2 in open-access papers (continued):
Sharing a sentence is not in itself a finding about the gene and the disease.
triple-negative breast carcinoma (52 papers, 2007 to 2026). An invasive breast carcinoma which is negative for expression of estrogen receptor (ER), progesterone receptor (PR), and human epidermal growth factor receptor 2 (HER2). "In the present study, we found that TMPRSS4 down-regulation improved the apoptosis effect of ionizing radiation on triple negative breast cancer associated with inhibition of expression of Bcl2 and increased of Bax and Caspase3." (PMID 31870109, 2019). "Furthermore, BCL2 expression in associated with poor response to Anthracycline-based chemotherapy in Triple negative breast cancers." (PMID 26405647, 2015). "Older women with triple-negative breast cancer exhibited less aggressive features, including lower Ki67, higher androgen receptor, and higher Bcl2 expression." (PMID 40373794, 2025). "Doxorubicin-loaded AuNPs (Dox-Bcl2-AuNPs) conjugated with siRNAs targeted the anti-apoptotic gene Bcl-2, significantly reducing its expression in triple-negative breast cancer cells and enhancing clonogenic survival." (PMID 40390104, 2025). "Immunohistochemistry suggests that this tumor is a triple-negative breast cancer positive for E-cadherin membrane and Bcl-2, which are all consistent with the results of this paper." (PMID 41040523, 2025). "For example, PARP inhibitors enlarged the antitumor activity of sacituzumab govitecan in triple-negative breast cancer and BCL-2/XL inhibitors Enhances the cytotoxicity of T-DM1." (PMID 38443386, 2024). "Another study analyzed data from 64 triple-negative breast cancers and reported that high expression of BCL2 is an independent adverse prognostic factor regarding overall survival." (PMID 34099764, 2021). "In another study, radiotherapy resulted in the activation of STAT3 and Bcl-2 in triple-negative breast cancer." (PMID 32872659, 2020). "Potential STAT3 inhibitors can decrease the production of ROS and down-regulate phosphorylation of STAT3 and Bcl-2, restoring sensitivity to radiation, which offers an effective approach for treating triple-negative breast cancer cells." (PMID 32872659, 2020). "In vitro studies show that the water extract of XHP can induce apoptosis of Hs578T triple negative breast cancer cells through an intrinsic Bcl-2-independent pathway to play an antitumor effect." (PMID 29849718, 2018). "In the present study, we have demonstrated that eIF4E induced cisplatin-resistance in ESCC mainly by promoting PI3K/AKT pathway and increasing Bcl-2/Bax ratio, which is similar to eIF4E in triple-negative breast cancer cells." (PMID 27588477, 2016). "Triple negative breast cancer patients showed statistically higher nuclear grade, and lower bcl-2 positive rate than non-triple negative breast cancer patients." (PMID 17976237, 2007). "Similarly, PARP inhibitors enhance the antitumor activity of sacituzumab govitecan in triple-negative breast cancer and BCL-2/XL inhibitors enhance the cytotoxicity of T-DM1." (PMID 37120688, 2023). "The inhibition of mitochondrial bioenergetics promotes an early induction of intrinsic pathway (mitochondrial pathway) apoptosis by ABT-199, a BCL2-selective inhibitor with cytotoxic action in several cancer cells, including triple-negative breast cancer cells." (PMID 37242775, 2023). "Also, we studied the relation between beclin-1 and Bcl-2 and their prognostic relevance in triple negative breast cancer." (PMID 36939902, 2023). "Our analysis dealt with a double-edged sword with the BH4 domain as a novel site for the targeted inhibition of BCL-2, on one side, and triple-negative breast cancer on the other side, and proposed covalent modification as a plausible solution for tackling these two challenges." (PMID 36358660, 2022).
triple-negative breast carcinoma (continued). "Cats with spontaneous Bcl-2-positive FMCs could be useful in preclinical trials evaluating anti-Bcl-2 strategies for chemoresistant luminal or triple-negative breast cancers." (PMID 30630524, 2019). "PD-L1 knock-out by CRISPR/Cas9 has proven effective in making triple negative breast cancer cells susceptible to chemotherapy through a reduced activation of p38 MAPK signalling pathway, that is dependent on the association of DNA-PKcs and B7-H1 followed by a downregulation of Bcl-2." (PMID 39696697, 2024). "For ginsenoside-induced apoptosis in triple-negative breast cancer cells, the mechanism is mainly through inhibiting NF-κB activation, decreasing NF-κB p65 and Bcl-2 protein expression, and increasing the ratio of Bax and caspase-3 protein expression to Bax/Bcl-2 to achieve therapeutic efficacy." (PMID 37749560, 2023). "Our study’s findings reveal a significant decrease in Bcl-2 phosphorylation following DDC treatment, with reductions of 97% in luminal A and 78% in triple-negative breast cancer (TNBC) cells." (PMID 38475417, 2024). "Recently, in triple-negative breast cancer cells MDA-MB-321, its activity was related to the decrease in CD44, CD24, Bcl2, release of Cytochrome c to the cytoplasm, and mitochondrial reduction." (PMID 38255214, 2024). "In triple-negative breast cancer (TNBC), TMPRSS4 inhibited TNBC apoptosis induced by 6 Gy IR, and the expression of Bax and Caspase 3 was overexpressed, while the expression of Bcl2 was downregulated, and radiotherapy sensitivity was decreased." (PMID 34528498, 2021). "To evaluate the co-expression of EGFR and BCL-2/XL within patient triple-negative tumors, we utilized a human tumor microarray (HTMA-240) comprising triple-negative breast cancers." (PMID 33256808, 2020). "miR-200bc/429 cluster modulates multidrug resistance of human cancer cell lines by targeting Bcl-2 and XIAP; microRNA-200c downregulates XIAP expression to suppress proliferation and promote apoptosis of triple-negative breast cancer cells." (PMID 32309578, 2016). "ABT-737, which targets BCL-2, BCL-XL, and BCL-W, was found to potentiate the response to docetaxel in PDX models of triple-negative breast cancer, suggesting that elevated BCL-2 expression in this subtype constitutes a predictive marker." (PMID 25849559, 2015). "Together, these findings suggest that the HA/CD44-induced c-Jun signaling plays a pivotal role in miR-21 production leading to survival protein (Bcl-2/IAP) upregulation and chemoresistance in triple negative breast cancer cells such as MDA-MB-468 cell line." (PMID 24606718, 2014). "Clinically, tumours with high BCL-2 expression show poor pathological responses to chemotherapy, and combinations of docetaxel with BCL-2 inhibitors, such as venetoclax, are under investigation in triple-negative breast cancer." (PMID 40806254, 2025). "Instead, the downregulation of X-linked inhibitor of apoptosis (XIAP) and survivin, two pro-survival proteins, under Rac inhibition by NCS23766 was shown to promote cell death in triple-negative breast cancer cells regardless of Bcl2 and cyclin D1 expression." (PMID 37316799, 2023). "Some studies, however, have shown that Bcl-2 expression is an independent prognostic factor, even in hormone receptor-negative or triple-negative breast cancers." (PMID 37370761, 2023). "Similarly, paclitaxel-resistant triple-negative breast cancer cells were more sensitive to ABT263 than their parental counterparts indicating that, at least in some tumour types, also BCL2 and BCL-XL may be highly promising targets." (PMID 37723317, 2023). "However, few studies have explored the prognostic significance of Bcl-2 in triple-negative breast cancers, i.e., those that are negative to ER, PR, and Human Epidermal growth factor Receptor-2 (HER2)." (PMID 30630524, 2019).
triple-negative breast carcinoma (continued). "Bcl-2 expression is an independent poor prognostic factor in patients with hormone receptor-negative or triple-negative breast cancers, especially in the absence of adjuvant therapy, suggesting that the anti-apoptotic nature of Bcl-2 is clearly exhibited under such conditions." (PMID 26472348, 2015). "Bcl-2 expression is an independent poor prognostic factor in patients with hormone receptor-negative or triple-negative breast cancers, especially in the absence of adjuvant therapy, suggesting that the anti-apoptotic effect of Bcl-2 is clearly exhibited under such conditions." (PMID 26472348, 2015).
endometrial cancer (50 papers, 2004 to 2025). Primary or metastatic malignant neoplasm involving the endometrium (mucous membrane that lines the endometrial cavity). "Surprisingly, it has been reported that increased Bcl-2 expression is associated with some favorable prognostic factors in endometrial carcinoma." (PMID 31861952, 2019). "We examined the relationship between BCL-2 gene family variants and endometrial cancer risk among 1,028 patients and 1,922 age-matched community controls from Shanghai, China." (PMID 23637776, 2013). "To date, no genetic association studies have been published on the role of BCL-2-gene family variants in the development of endometrial cancer." (PMID 23637776, 2013). "In summary, we found that two independent SNPs in the BCL2 gene were associated with endometrial cancer risk among Chinese women." (PMID 23637776, 2013). "Significant associations with endometrial cancer risk were found for 9 SNPs in the BCL2 gene (P trend<0.05 for all)." (PMID 23637776, 2013). "Effects of BCL2 gene variants on associations between risk scores for established risk factors and endometrial cancer risk, the Shanghai Endometrial Cancer Genetics Study (SECGS)." (PMID 23637776, 2013). "We investigated whether genetic variants in the BCL-2-family genes BAD, BAX, BCL2 or BAK1 are associated with endometrial cancer risk." (PMID 23637776, 2013). "Genetic polymorphisms in the BCL2 gene may be associated with the risk of endometrial cancer in Chinese women." (PMID 23637776, 2013). "Bcl-2 persistence is frequently associated with endometrial carcinoma, and failure to inactivate Bcl-2 expression probably is related to the development of endometrial carcinoma." (PMID 24314145, 2013). "The study also revealed that the expression of miR-29b is associated with the increased sensitivity of endometrial cancer cells to cisplatin and the cisplatin-induced enhancement of apoptosis through the regulation of BAX and Bcl-2 expression." (PMID 39518001, 2024). "AM, by upregulating the Bcl-2 antiapoptotic protein expression, blocks cell death by hypoxia in endometrial cancer cells." (PMID 36980580, 2023). "More precisely, PGC-1α synergized via the mitochondrial pathway with estrogen to ensure endometrial cancer cell survival, whereas PGC-1α knockdown promoted apoptotic cell death through a reduction in Bcl2 and an increase in Bcl2-associated X (Bax) expression." (PMID 37298140, 2023). "The expression of GAS5 is reduced in T2D patients with endometrial cancer and its over-expression induces BCL2, also reducing the expression of the pro-apoptotic proteins BCL2 associated agonist of cell death (BAD) and BAX." (PMID 36290744, 2022). "Over-expression of the microRNA led to decrease of Bax pro caspase 3, p27, in turn, expression of Bcl-2 was silenced in endometrial cancer cells inducing apoptosis." (PMID 33123872, 2021). "For example, miR-125b-5p can enhance gallbladder cancer cell sensitivity to chemotherapy by downregulating BCL2 expression 26, while CDKN2B-AS1 modulates the miR-125a-5p/BCL2 axis in endometrial carcinoma to enhance paclitaxel sensitivity." (PMID 34790046, 2021). "The estrogen signaling pathway, which is highly associated with the development of endometrial cancer, showed enrichment of four differentially expressed ARGs (ITPR1, FOS, PRKCD, and BCL2)." (PMID 33109128, 2020). "Frameshift mutations in Bax, leading to loss of expression, which in turn impede apoptosis through an increased Bcl‐2/Bax ratio, were previously identified in ~10% of endometrial cancers." (PMID 30537101, 2019). "Curcumin has been shown to promote cell apoptosis by downregulating Ets-1 and Bcl-2 in endometrial carcinoma." (PMID 32083122, 2019). "In endometrial cancer cells, cisplatin increases Bcl-2 expression via activation of protein kinase C and Akt2." (PMID 25885284, 2015). "Common genetic variants in the BCL-2-family genes BCL2, BAD, BAX and BAK1 were comprehensively evaluated for associations with endometrial cancer risk." (PMID 23637776, 2013).
endometrial cancer (continued). "Over expression of BCL2 slows down cell growth and very high expression can promote cell death, while lower BCL2 expression can be a sign of inhibition of apoptosis in human breast and endometrial carcinoma tissues." (PMID 23637776, 2013). "Laboratory studies have also demonstrated that BCL2 gene expression is related to the degree of aggressiveness and differentiation in endometrial carcinoma." (PMID 23637776, 2013). "Over expression of the anti-apoptotic BCL2 gene has been observed in various human cancer tissues, including breast, colon, thyroid and endometrial carcinomas." (PMID 23637776, 2013). "Modulation of the Bcl-2/Bax ratio facilitates the formation of the apoptosome thus resulting in apoptotic cell death of the SDGE-treated endometrial cancer cells." (PMID 23300887, 2012). "Similarly, PS treatment has been shown to promote a concentration-dependent increase in Casp-3 and Bax but decrease in Bcl-2 ratio in pancreatic, breast, prostate, and endometrial cancer cell lines." (PMID 39474042, 2024). "A few of the markers that are available for endometrial carcinoma include BCL-2 and HER2/neu." (PMID 36751174, 2023). "The aim of the study was to study the immunohistochemical expression of B-cell lymphoma 2 (BCL-2) in endometrial carcinoma and to study the correlation of BCL-2 expression with hormone receptor status and transforming growth factor receptors in endometrial carcinoma." (PMID 36751174, 2023). "Previous evidence showed that CCAT2 knockout repressed endometrial cancer cell growth and invasion by binding to miR‐216b, and miR‐216b could negatively regulate Bcl‐2 that could active the mTOR pathway." (PMID 35170195, 2022). "Expression of BCL2 (targeted by two enhancers chr15:54202002–54203000 and chr15:54203002–54203600) is significantly more frequent in early clinical stages in both types of endometrial cancer." (PMID 34879086, 2021). "The role of genetic variants in BCL-2 genes and their interactions with non-genetic factors in the development of endometrial cancer has not been investigated in epidemiological studies." (PMID 23637776, 2013). "Both BAG1 and bcl-2 play a role in the inhibition of apoptosis in endometrial carcinoma." (PMID 17645802, 2007). "Regarding the correlation between Bcl-2 expression and tumour-proliferative activity, an inverse correlation between them was reported in breast, lung and endometrial carcinomas." (PMID 14710230, 2004). "The 9 disease-associated SNPs in the intronic region of BCL2 do not appear to alter amino acids, so their relationship to the underlying biology of endometrial cancer remains unclear." (PMID 23637776, 2013). "However, in our study, we found no modifiable effect of two independent SNPs within the BCL2 gene on associations between non-genetic factors, including hormonal factors, and endometrial cancer risk." (PMID 23637776, 2013). "In human endometrial cancer cells, EGCG treatment resulted in the suppression of anti-apoptotic protein BCL-2, the upregulation of pro-apoptotic BAX, and the activation of caspase-3 and PARP." (PMID 37189618, 2023). "There was an inverse correlation between ER, PR, BCL-2, and HER2/neu receptors expression in endometrial carcinomas included in the study." (PMID 36751174, 2023). "BCL-2 expression is progressively low in complex hyperplasia with atypia and with grade III, advanced endometrial carcinomas." (PMID 36751174, 2023). "Finally, immunohistochemical analysis of tumor tissues collected from subcutaneous tumorigenesis experiment in nude mice confirmed that SNORD89 overexpression in vivo could decrease the expression of Bim protein and increase the expression of Bcl-2 protein in endometrial cancer cells." (PMID 35790714, 2022). "miR-204 is reported to act as a tumor suppressor in a variety of cancers through different mechanisms including down-regulation of Bcl-2, NTRK2 in neuroblastoma cancer and suppression of invasion in endometrial cancer mediated by FOXC1 regulation." (PMID 24025188, 2013).
endometrial cancer (continued). "In endometrial cancer, hesperidin has been shown to suppress non-genomic estrogen receptor signaling, increase the Bax/Bcl-2 ratio, and enhance Caspase-3 activity." (PMID 41010990, 2025). "The ECC-1 line was chosen because it represents a well-differentiated, estrogen-responsive endometrial carcinoma subtype that stably expresses key apoptotic and angiogenic markers such as HIF-1α, VEGF, Bax, and Bcl-2, making it an appropriate model for hypoxia-related investigations." (PMID 41470183, 2025). "The study demonstrated a connection between miR-135a and the increased proliferation and invasion of the tumor process, as well as showing that this marker inhibits the apoptosis induced by cisplatin in endometrial cancer cells by regulating the expression of BAX and Bcl-2." (PMID 39518001, 2024). "In endometrial carcinoma, inhibition of PARR through Bcl-2/Caspase3 pathways could hinder apoptosis, fostering carcinogenesis." (PMID 38370348, 2023). "Number of cases with types of endometrial carcinoma and expression of ER, PR, HER2/neu, and BCL-2." (PMID 36751174, 2023). "In addition, overexpression of lncRNA TDRG1 promotes the viability, invasion and migration of endometrial cancer cells, inhibits cell apoptosis, and upregulates the expression of VEGF-A, PI3K, Bcl-2, MMP2 and surviving." (PMID 36338699, 2022). "Therefore, we examined the potential participation of c-Abl, B-cell lymphoma-2 (bcl-2), caspase-9, caspase-3 and PARP in the cisplatin-induced MLH1/c-Abl apoptosis signaling pathway in endometrial carcinoma cells via Western blot analysis." (PMID 30594176, 2018). "Most such studies have found low or no expression of BCL2 in endometrial carcinoma, although the evidence was not entirely consistent." (PMID 23637776, 2013). "Atovaquone inhibited the viability of human ovarian and endometrial cancer cell lines of human (OVCAR-3, SKOV-3 and ECC-1) and murine (ID8) origin by inducing apoptosis as indicated by an increase in annexin V on the cell surface, cleaved caspase 3 and cleaved caspase 9 and a decrease in Bcl-2." (PMID 35565426, 2022). "In endometrial carcinomas, bcl-2 expression does not provide prognostic information." (PMID 17645802, 2007). "Studies have shown that shikonin can inhibit the proliferation and induce apoptosis of endometrial cancer Ishikawa cells and human ovarian cancer SKOV-3 cells in vitro, and the mechanism may be related to up-regulation of Bax expression and down-regulation of Bcl-2 expression." (PMID 35873044, 2022). "In this study, we aimed to investigate DFF45, BCL2 and DFF40 expression in endometrioid and non-endometrioid types of endometrial cancers (ECs)." (PMID 29653556, 2018). "Number of endometrial carcinoma cases that are ER, PR, HER2/neu, and BCL-2 positive or negative." (PMID 36751174, 2023).